PPARGC1A (PPARG coactivator 1 alpha)
Diseases named in the same sentence as PPARGC1A in open-access papers (continued):
Sharing a sentence is not in itself a finding about the gene and the disease.
heart failure (129 papers, 2008 to 2026). Inability of the heart to pump blood at an adequate rate to meet tissue metabolic requirements. "The development of heart failure is accelerated by Ppargc1a deficiency, suggesting that this coactivator may have a cardioprotective function." (PMID 20195525, 2010). "Nonetheless, individual deletion of Ppargc1a or Ppargc1b accelerates heart failure in response to increased workload imposed by transverse aortic constriction." (PMID 34360813, 2021). "Further, there are animal data to support a direct role for PPARGC1A in the development of heart failure." (PMID 19077249, 2008). "In addition, worsening-LVF was associated with altered expressions of genes pathologically relevant to heart failure, such asdownregulated apelin receptors and upregulated peroxisome proliferator-activated receptor gamma coactivator 1-alpha (PPARGC1A)." (PMID 32708358, 2020).
Hepatic steatosis (104 papers, 2008 to 2026). Steatosis is a term used to denote lipid accumulation within hepatocytes. "Throughout our in vivo experiment, CEL upregulated Ppargc1a gene expression that was suppressed by WD/FG, resembling liver-specific-deficient PGC-1α mice with manifested hepatic steatosis." (PMID 39968178, 2025). "PPARGC1α has been shown to induce expression of Clock, Bmal1, Rev-erbα, and Rev-erbβ and increase transcriptional activity of RORα, with deficiency of this protein contributing to hepatic steatosis after short-term starvation." (PMID 23951220, 2013). "It was found that the PPARGC1A knockout mice exhibited marked hepatic steatosis due to a combination of reduced mitochondrial respiratory capacity and increased expression of lipogenic genes." (PMID 34055713, 2021). "It is worth noting that a recent study has shown that p38 inhibition enhanced parenteral nutrition-induced hepatic steatosis and attenuated the expression of Cpt1a, Acox1, and Ppargc1a in a rat model." (PMID 30563203, 2018). "Ppargc1a is a potent transcriptional activator of glucose and lipid metabolism linking nutritional and hormonal signals and energy metabolism; and Ppargc1a-null mice develope systemic dyslipidemia and hepatic steatosis." (PMID 23783067, 2013). "Recent evidence also implicates PPARGC1A in the homeostatic control of systemic energy metabolism, and PPARGC1A knockout mice have been reported to develop hepatic steatosis due to a combination of reduced mitochondrial respiratory capacity and increased expression of lipogenic genes." (PMID 18588668, 2008). "The expression of PPARG coactivator 1 alpha (Ppargc1a), which is involved in glucose and fatty acid metabolism, and cell death-inducing DFFA-like effector c (Fsp27), a lipid droplet protein involved in hepatic steatosis, were also significantly reduced." (PMID 39956880, 2025). "In addition, the higher circulating FFAs with KrO may result in a higher influx of fat to the liver, thereby counteracting the beneficial effects on hepatic fat oxidation (i.e., PPARA, ACOX1, PPARGC1A), altogether leading to comparable hepatic steatosis as in the HFD controls." (PMID 34444996, 2021).
Hyperglycemia (95 papers, 2007 to 2026). An increased concentration of glucose in the blood. "Ppargc1αis a key regulator of hepatic gluconeogenesis that contributes to circulating hyperglycemia, and liver-specific Ppargc1α-deficient mice have reduced Pck1 and G6pc expression and mild hypoglycaemia." (PMID 25405530, 2014). "Interestingly, altered methylation of the peroxisome proliferator-activated receptor-γ co-activator 1 α (PPARGC1A) gene mediated the association between maternal hyperglycemia and the cord blood leptin levels." (PMID 34946940, 2021). "In addition, our mediation analyses support that epigenetic regulation of PPARGC1α is implicated in the link between maternal hyperglycemia and elevated cord blood leptin levels, considered as a marker for adiposity in offspring." (PMID 27340502, 2016). "Ghrelin-induced hyperglycaemia in rats is associated with increased hepatic glucose-6-phosphatase gene expression and with suppressed Akt phosphorylation, reduced phosphorylation of glycogen synthase kinase 3, and an increase in Ppargc1a gene expression." (PMID 24555152, 2013). "Therefore, increased expression in Ppargc1a might be associated with improvement of hyperglycemia in the exercise GK rats." (PMID 31338039, 2019). "Work from our group has demonstrated that intrauterine hyperglycaemia inhibited the expression of Ppargc1α and uncoupling protein (Ucp1) in BAT, leading to impaired mitochondrial thermogenesis." (PMID 39043630, 2024). "In summary, we demonstrated that short-term foetal exposure to hyperglycaemia downregulated Ppargc1α by inhibiting CREB phosphorylation in the SKM of male offspring, leading to abnormal mitochondrial biogenesis and lipid oxidation." (PMID 39043630, 2024). "One should note that we observed a significant increase in the expression of the Ppargc1a gene both under conditions of normoglycemia and hyperglycemia." (PMID 37507997, 2023). "In parallel, the mRNA level of the Ppargc1a and Mfn2 genes in fibroblasts exposed to hyperglycemia was reduced." (PMID 37569860, 2023). "In the current study, we tested in two independent birth cohorts whether the fetal exposure to maternal hyperglycemia is associated with placental DNA methylation variations in genes involved in BAT/wBAT genesis, specifically targeting the PRDM16, BMP7, CTBP2, and PPARGC1α gene loci." (PMID 27340502, 2016). "Thus, whilst male and female IVF offspring both display hyperglycemia, this may be due to alternative activation of Ppargc1α or Srebf1 pathway." (PMID 25405530, 2014). "Foetal exposure to hyperglycaemia decreased the ratio of phosphorylated CREB and reduced the transcription of Ppargc1α, which inhibited the transcription of downstream genes involving in mitochondrial biogenesis and oxidative metabolism." (PMID 39043630, 2024). "Hyperglycemia increased the placental expression of miR-130b, which in turn suppressed PPARG coactivator 1 alpha (PPARGC1A), a master regulator of oxidative phenotype." (PMID 33081177, 2020). "Of interest, Ppargc1a and other gluconeogenic genes were induced in the liver of POKO mice compared to that of ob/ob mice, suggesting a potential mechanism contributing to marked hyperglycaemia in POKO mice." (PMID 17465682, 2007).
Parkinson disease (85 papers, 2011 to 2026). A progressive degenerative disorder of the central nervous system characterized by loss of dopamine producing neurons in the substantia nigra and the presence of Lewy bodies in the substantia nigra and locus coeruleus. "Genetic studies in humans have suggested associations of the PPARGC1A locus with Alzheimer’s, Huntington’s, and Parkinson’s disease and amyotrophic lateral sclerosis." (PMID 31471878, 2020). "PPARGC1A has also been implicated in the pathogenesis of other neurodegenerative disorders, namely Huntington’s and Parkinson’s diseases." (PMID 31283791, 2019). "Interestingly, genetic studies implicated the CNS-specific PPARGC1A region in the pathogenesis of Parkinson’s disease." (PMID 31471878, 2020). "Deregulation of the miR-193b-3p/PPARGC1α pathway directly leads to alterations in insulin expression, underscoring the importance of insulin in Parkinson’s disease." (PMID 41009376, 2025). "PPARGC1A (PGC-1α, PPARG Coactivator 1 Alpha), is another striated muscle/mitochondria-associated gene involved in Parkinson’s disease." (PMID 35076500, 2021). "Clinical characteristics and levels of PPARGC1A methylation and mRNA of Parkinson’s disease patients and controls." (PMID 32174806, 2020). "For instance, multiple PPARGC1A transcripts are more abundant and CNS-specific in Parkinson’s disease (PD)." (PMID 31576243, 2019). "The Gly482Ser PPARGC1A polymorphism has been associated with T2DM, hypertension, and Parkinson's disease." (PMID 26185753, 2015). "Furthermore, in patients with Parkinson’s disease, deregulation of miR-193b-3p levels has been observed (the levels change as the disease progresses) which, in turn, regulates the expression of PPARGC1α." (PMID 41009376, 2025). "Correlations between PPARGC1A methylation level with Parkinson’s disease clinical data." (PMID 32174806, 2020).
sarcopenia (85 papers, 2010 to 2026). Progressive decline in muscle mass due to aging which results in decreased functional capacity of muscles. "In our qPCR assays, PPARGC1A was down‐regulated in the sarcopenia versus control groups (P < 0.05)." (PMID 41460756, 2026). "In contrast, sarcopenia group showed remarkably reduced PCTP (P < 0.001), SREBF2 (P < 0.001), and PPARGC1A (P < 0.05) levels." (PMID 41460756, 2026). "The qPCR results demonstrated that FABP3 (P < 0.001), PECR (P < 0.01), and OPN3 (P < 0.001) expression markedly increased in D‐gal‐induced sarcopenia compared with control groups, whereas PCTP (P < 0.001), SREBF2 (P < 0.001), and PPARGC1A (P < 0.05) levels dramatically decreased." (PMID 41460756, 2026). "FABP3, PPARGC1A, and SREBF2 received the highest relevance scores, indicating that these genes may serve as more prominent mediators linking sarcopenia with fatty acid metabolism." (PMID 41460756, 2026).
Sepsis (80 papers, 2010 to 2025). Sepsis is defined as life-threatening organ dysfunction caused by a dysregulated host response to infection. "Ppargc1a and Ppargc1b expression increase functional mitochondrial mass and preserved mitochondrial function, e.g. in skeletal muscle, is associated with better outcomes in sepsis." (PMID 21966468, 2011). "Therefore, we investigated Ppargc1a expression (encodes Pgc1α) in the diaphragm during sepsis." (PMID 34557108, 2021). "Expression of the key nuclear transcription factor regulating lipid metabolism, PPARα (PPARa) and its co-activator PGC1α (Ppargc1a) were downregulated in acute sepsis, but increased above healthy levels in prolonged sepsis." (PMID 39821755, 2025). "The PGC family of transcriptional co-activators (PGC-1α [Ppargc1a], PGC-1β [Ppargc1b], and PRC [Pprc]) coordinates the upregulation of mitochondrial biogenesis, and Ppargc1a is known to be activated in response to mitochondrial damage in sepsis." (PMID 20657826, 2010). "This would translate to therapeutic potential if Ppargc1a or Ppargc1b gene activation could be shown to improve recovery or lessen mortality in clinical sepsis." (PMID 20657826, 2010). "Thus mmu-mir-202-3p expression correlates with decreased Ppargc1a and Ppargc1b in this in vivo model of sepsis." (PMID 20657826, 2010). "However, mRNA levels of Ppargc1a, the master regulator of mitochondrial biogenesis and function, and Sdhb, crucial component of the succinate dehydrogenase complex, remained unaltered after five days of sepsis." (PMID 41385533, 2025). "This includes the metabolic and mitochondrial biogenesis master co-activators, Ppargc1a (PGC-1α) and Ppargc1b (PGC-1β) in Staphylococcus aureus (S. aureus) sepsis." (PMID 21966468, 2011). "Thus, our findings that Ppargc1a and Ppargc1b are co-regulated in response to sepsis, and that mRNA stability for each correlates inversely with the expression mir-202-3p, indicate that both may serve pro-survival functions in sepsis." (PMID 20657826, 2010). "Using TLR3 agonist PolyI:C to induce IRF-7 in TLR2−/− mice, we found no increase in basal Ppargc1a mRNA levels, but we did rescue the Ppargc1a response in sepsis." (PMID 21966468, 2011). "If Ppargc1a/b activation by IRF-7 translates to the clinical setting, it should be possible to establish whether this pathway protects metabolic and organ function during sepsis." (PMID 21966468, 2011). "Ppargc1a/b activation did not require NF-kβ, but did require an interferon response factor (IRF), because neither gene was activated in IRF-3/7 double-knockout mice in sepsis, but both were activated normally in Unc93b1-deficient (3d) mice." (PMID 21966468, 2011).
cardiac hypertrophy (72 papers, 2013 to 2025). "Other endurance genes change their expression in the heart in endurance-exercising mice (especially Ppargc1a appears to increase during physiological cardiac hypertrophy) or are associated with cardiac phenotypes in GWAS studies." (PMID 30967789, 2019). "Interestingly, some of these targets such as Tgfb1, Hras, Fgf2, and Ppargc1a have been implicated in cardiac hypertrophy suggesting that low-dose dasatinib indeed impacts genes that affect heart growth and remodeling." (PMID 33689087, 2022). "Furthermore, anti-miR-199a attenuates cardiac hypertrophy and restores cardiac function in vivo through the PPARGC1A (PGC-1α)/ESRRA (ERRα) axis." (PMID 34869689, 2021).
Huntington disease (65 papers, 2008 to 2025). Huntington disease (HD) is a rare neurodegenerative disorder of the central nervous system characterized by unwanted choreatic movements, behavioral and psychiatric disturbances and dementia. "There is a brain specific promoter 587kb upstream of human PPARGC1A, which is located in a genomic region associated with age of onset of Huntington’s disease and relevant here is that hippocampal PGC-1α expression is decreased in the AD brain." (PMID 31283791, 2019). "Here we report the presence of a common polymorphism and a common haplotype in PPARGC1A that are associated with a delay in age at onset of motor symptoms in patients with Huntington's disease." (PMID 19133136, 2009).
cardiomyopathy (64 papers, 2009 to 2025). A disease of the heart muscle or myocardium proper. "The review identified key gene variants affecting athletic performance: endurance (AMPD1, PPARGC1A), power (ACTN3, NOS3), strength (PPARG), and injury susceptibility (COL5A1, MMP3), while also examining inherited conditions like cardiomyopathies (MYH7, MYBPC3)." (PMID 40724525, 2025). "PPARGC1A is a key regulator of cardiac energy metabolism; overexpression of PPARGC1A in the murine heart leads to a modest increase in mitochondrial number, derangements of mitochondrial ultrastructure, and development of cardiomyopathy." (PMID 20426853, 2010).
steatosis (61 papers, 2008 to 2025). Increased lipid within the cytoplasm of cells. "Liver histology revealed amelioration of high-fat diet-induced steatosis, which corresponded to upregulation of Ppargc1α, Ppar1α, and Fgf2145–47 by DG, AD and IKA." (PMID 29273768, 2017). "We recruited 115 patients with biopsy-proven NAFLD, 65 with NASH and 50 with simple steatosis, and 441 healthy control subjects and investigated 15 SNPs of PPARGC1A." (PMID 18588668, 2008). "The moderate but consistent upregulation of Fgfr1 and Ppargc1a observed in mice with less hepatic involvement supports the hypothesis that these genes may participate in adaptive metabolic pathways that mitigate steatosis." (PMID 41465464, 2025). "PPARGC1A overexpression in hepatocytes enhances mitochondrial function and lipid oxidation, thereby reducing triglyceride accumulation, as observed in this study, and acting as a protective factor against steatosis." (PMID 41465464, 2025). "The most upregulated genes associated with steatosis in the macaque alcohol liver disease model (PPARGC1A, IGFBP1, and FASN) were not altered by acute SIV infection." (PMID 38400071, 2024). "Valine and isoleucine disabled crucial switches of the anabolic pathways in steatosis (SREBPF1) and consequently activated regulators of mitochondrial (PPARGC1A) and lipid metabolism (AMPK)." (PMID 39459592, 2024). "In detail, we found the down expression of FABP1 (40 times) and APOC3 (11.98 times), PPARGC1A and GK (11 times), ABCA1 and SRBF2 (3 times) compared to the steatosis control." (PMID 36770927, 2023). "In our experiments, the downregulation of genes involved in lipid/cholesterol metabolism and transport (such as FABP1, APOC3, PPARGC1A, GK, ABCA1, and SRBF2) induced by curcumin treatment could explain the observed reduction of steatosis and lipid content." (PMID 36770927, 2023). "Consistent with the development of steatosis in the HFD group, important upstream regulators involved in lipid catabolism (peroxisomal acyl-CoA oxidase 1 (ACOX1), AMP kinase (AMPK) and mitochondrial biogenesis (PPARGC1a) were all inactivated with HFD." (PMID 35782914, 2022). "The prominent hepatic increase in Ppargc1a mRNA in the HFD-fed group might be due to a compensatory response to enhance mitochondrial biogenesis and function in a steatosis environment, foster fatty acid oxidation, and reduce TG accumulation and secretion." (PMID 34850865, 2021). "The treatment with curcumin-andrographolide in association maintained the ability to regulate in a negative manner FABP1 (15.96 times), PPARGC1A (7.85 times), GK and ABCA1 (4 times), and APOC3 (2.04 times) in respect to the steatosis control." (PMID 36770927, 2023).
metabolic syndrome (59 papers, 2008 to 2026). A cluster of metabolic risk factors for CARDIOVASCULAR DISEASES and TYPE 2 DIABETES MELLITUS. "Further stratification using adult treatment panel III criteria for metabolic syndrome revealed that PCOS patients with one or more risk factors (59.43%) had higher PPARGC1A methylation and lower mtDNA content than those without risk factors (41.57%)." (PMID 40525011, 2025).
diabetic nephropathy (58 papers, 2014 to 2026). "Consistently, PPARGC1A (rs8192678) was reported to be associated with T2DM in a European population, as well as diabetic nephropathy (DN) in an Asian Indian population." (PMID 25302081, 2014).